EGFR (epidermal growth factor receptor)
Diseases named in the same sentence as EGFR in open-access papers (continued):
Sharing a sentence is not in itself a finding about the gene and the disease.
lung cancer (continued). "The EGFR mutation is the most common identified gene alteration among lung cancer patients after a large amount research using a variety of methods, such as in vitro cell culture, ex vivo, in vivo animal models and human samples." (PMID 35055327, 2021). "In this study, we examined how mutation influences the crosstalk between EGFR, who plays a significant role in lung cancer progression, and its RTK partners in downstream signaling pathways." (PMID 34112110, 2021). "Inherent and acquired resistance in EGFR-mutated lung adenocarcinoma pose a major challenge to outcome improvement in lung cancer treatment." (PMID 34202748, 2021). "Epidermal growth factor receptor (EGFR) mutations in non–small-cell lung cancer predict sensitivity to EGFR tyrosine kinase inhibitors (TKIs)." (PMID 33430803, 2021). "Epidermal growth factor receptor‐tyrosine kinase inhibitor (EGFR‐TKI) therapy is the standard treatment for advanced non‐small cell lung cancer (NSCLC) harboring common EGFR mutations, such as exon 19 deletion or L858 point mutation." (PMID 33124128, 2021). "Major EGFR mutations (>90% of EGFR-mutated lung cancer) are highly sensitive to EGFR tyrosine kinase inhibitors (TKIs)." (PMID 33863983, 2021). "In the literature, it has been described how adrenal involvement confers worse prognosis in both wild type and EGFR mutated lung cancer." (PMID 34465283, 2021). "EGFR mutations are linked with good prognosis in lung cancer patients mainly attributed to the treatment of tyrosine kinase inhibitor (TKI), but also seen in surgically resected non-small cell lung cancer (NSCLC) without receiving TKI." (PMID 33956842, 2021). "Epidermal growth factor receptor (EGFR) tyrosine kinase inhibitors are the standard treatment for patients with non‐small cell lung cancer (NSCLC) harboring EGFR mutations." (PMID 33533191, 2021). "We included our recent paper describing the generation of DTCs from multiple EGFR-mutated lung cancer cell lines." (PMID 34202566, 2021). "In gefitinib-sensitive lung cancer cells with EGFR mutations and amplifications, continued activation of PI3K signaling by the PIK3CA oncogenic mutant was sufficient to abrogate gefitinib-induced apoptosis." (PMID 33997043, 2021). "For example, lung cancer cells with EGFR gene mutations in exons E19 and E21 are more sensitive to EGFR-TKI-mediated cell apoptosis, while cells with a mutation in exon 20 have increased resistance to EGFR-TKI-mediated cell apoptosis." (PMID 34217313, 2021). "This study aimed to examine EGFR mutations of primary lung adenocarcinoma in sputum samples using ddPCR and compare it with an EGFR mutation in surgically resected lung cancer." (PMID 33757469, 2021). "Patients with an epidermal growth factor mutation (EGFR), a subgroup of the patients with lung cancer, seem to develop more bone metastases than other patients with lung cancer." (PMID 34201833, 2021). "Subsequent to the first report of IGF-1R activation in 2010, AXL, Notch3, and fibroblast growth factor receptor 3 (FGFR3) are identified as receptor tyrosine kinases (RTKs) that cause drug tolerance in lung cancers with EGFR mutations." (PMID 34202566, 2021). "Our findings, taken together, highlighted the role of Notch1 in determining the maintenance or loss of epithelial phenotype in lung cancer cells exposed to EGFR TKIs." (PMID 33922104, 2021). "We provide a discussion of available combination and novel therapies that are being studied to improve outcomes and target resistant mechanisms in EGFR-mutated lung cancer." (PMID 34202748, 2021).
lung cancer (continued). "Ras–PI3K interaction is also required for tumor progression of WT Ras cancers since removal of Ras–PI3K interaction in an EGFR mutant lung cancer model caused important tumor regression." (PMID 34356110, 2021). "Afatinib is an irreversible inhibitor of EGFR, HER2, and HER4 approved for the treatment of lung cancer with EGFR mutations." (PMID 34016991, 2021). "A 2016 study showed that MALT1 (mucosa-associated lymphoid tissue 1) is involved in EGFR-induced NF-κB activation in lung cancer cells, and that MALT1 inhibition impaired EGFR-dependent NF-κB activation." (PMID 34206026, 2021). "Compound mutations, consisting of a common and an uncommon mutation, are more frequent than single mutations, harboring 2–25% of the EGFR mutation-positive lung cancers." (PMID 34809713, 2021). "KRAS and EGFR mutations are two of the most common drivers of lung cancer that are responsible for approximately 25 and 15% of all NSCLC cases." (PMID 33860729, 2021). "In this paper, we summarized current understandings of DTCs that counteract the cytotoxic effects of EGFR TKIs in lung cancers that harbor an EGFR mutation." (PMID 34202566, 2021). "EGFR-mutant lung cancer, with low TMB, and tumors with loss of neoantigen expression while on immunotherapy are relatively resistant to immune checkpoint therapy." (PMID 34391887, 2021). "PC9 cells (exon 19 E746_A750 del) are a lung cancer cell line that often acquires resistance to EGFR-TKIs through T790M secondary mutation." (PMID 33572269, 2021). "Most previous studies of EGFR mutation-positive lung cancer have reported the proportion of patients with EGFR mutations among the tested patients." (PMID 33961689, 2021). "Adenocarcinomas in non-smokers have some distinctive features arising from gene alterations, including a lower mutational load compared to other lung cancer histologies and oncogenic factors such as EGFR mutations or rearrangements of the ALK or ROS1 genes." (PMID 34857781, 2021). "Primary mutations in the EGFR gene are the most common driver of lung cancer initiation and progression." (PMID 34381712, 2021). "Afatinib is a first-line treatment option for patients with an advanced nonsmall cell lung cancer (NSCLC) expressing an epidermal growth factor receptor (EGFR) activating mutation." (PMID 34221011, 2021). "Among the various biomarkers associated with lung cancer, genetic alterations in epidermal growth factor receptor (EGFR) are perhaps the most notable biomarker affecting the management of NSCLC patients with BrM." (PMID 35145903, 2021). "For lung cancer patients with EGFR T790M mutation, osimertinib as first-line treatment or as subsequent treatment after initial targeted therapy should be given priority." (PMID 33992097, 2021). "The decreased stem cell markers of EMT and c-Met as well as overcoming drug resistance signaled the opportunities of the BJ extract for therapy of lung cancer harboring mutated EGFR." (PMID 35582384, 2021). "Further work in this space led to the identification of EGFR mutations in lung cancer, paving the way to precision medicine in lung cancer." (PMID 34572868, 2021). "Osimertinib shows strong clinical activity in first- and second-line treatment of nonsmall-cell lung cancer (NSCLC) patients with epidermal growth factor receptor (EGFR) mutations, especially EGFR T790M." (PMID 34987382, 2021). "Based on these results, the U.S. FDA granted mobocertinib Orphan Drug Designation for the treatment of lung cancer with HER2 mutations or EGFR mutations (including exon 20 insertion) in 2019." (PMID 39035769, 2021). "The mutational status of the epidermal growth factor receptor (EGFR) guides the stratification of non‐small cell lung cancer (NSCLC) patients for treatment with tyrosine kinase inhibitors (TKIs)." (PMID 33942501, 2021).
lung cancer (continued). "To compare the cellular landscape between two different molecular subtypes of lung cancer based on the EGFR mutation status, we prepared tumor specimens surgically resected from 10 patients with NSCLC in stages IA–IIIA: five EGFR-WT and five EGFR-MT." (PMID 34663810, 2021). "Current efforts to improve treatment in lung cancer patients focus largely on targeting secondary and tertiary mutations in EGFR kinase domain." (PMID 34359849, 2021). "In this study, EGFR germline and somatic variants were retrospectively reviewed from the next-generation sequencing results of 31,906 patients with lung cancer." (PMID 34869019, 2021). "A total of 15 lung cancer patients were recruited with 7 cases of wild-type EGFR and 8 cases with EGFR mutations." (PMID 34680445, 2021). "The findings revealed that lung cancer with the EGFR E746-A750 deletion mutation caused the antitumor immunity to be repressed by dendritic cells via exosomes." (PMID 33855679, 2021). "In our study, we found that ANF effectively represses the PKCί–ELF3 axis and inhibits tumor growth of lung cancer cells harboring EGFR mutation relevant to 1st-generation EGFR TKI resistance." (PMID 34830169, 2021). "According to the latest guidelines by the American College of Pathologists (2018), reflex molecular testing of EGFR gene mutations by next-generation sequencing method should be performed in all cases of primary lung cancer with adenocarcinoma component." (PMID 34181354, 2021). "Since EGFR-L858R is found in ~40% of EGFR-mutated lung cancers, it constitutes a promising, widely shared NeoAg target for TCR-T therapy of HLA-A*1101/EGFR-L858R lung cancer patients." (PMID 34572028, 2021). "Future researches were need to clarify the relationship of T lymphocytes and EGFR mutation in lung cancer." (PMID 33859531, 2021). "This review article details the progress of lung cancer treatments for a subtype known as non-small cell lung cancer with a special mutation of epidermal growth factor receptor (EGFR)." (PMID 34439273, 2021). "Despite the dramatic responses of lung cancers with EGFR mutations to EGFR-TKIs, the emergence of acquired resistance (AR) is almost inevitable." (PMID 33572269, 2021). "In lung cancer, most of the mutations of EGFR are caused by the rearrangement and amplification of the EGFR gene or the selective splicing of mRNA." (PMID 33633793, 2021). "Eight of the 9 patients with lung cancer were screened for epidermal growth factor receptor (EGFR) gene mutation, with 6 patients (75%) showing positive results for EGFR mutation." (PMID 33550544, 2021). "Epidermal growth factor receptor (EGFR) represents as the most frequently mutated driver gene in lung cancer." (PMID 34195081, 2021). "Approximately at the same time the anti-EGFR kinase inhibitor gefitinib showed antitumor activity against EGFR-mutated lung cancer." (PMID 34359977, 2021). "Gefitinib, a tyrosine kinase inhibitor (TKI), is an EGFR-blocking drug that is effective in the treatment of lung cancer with EGFR mutations; however, its benefits for HNSCCs are uncertain." (PMID 34262802, 2021). "EGFR copy gain and mutations were also identified in 13% and 15% patients, which is higher than previously reported frequency in Western lung cancer patients." (PMID 33403024, 2021). "Cardiac arrest occurred in an 85-year-old female administered osimertinib for advanced lung cancer expressing epidermal growth factor receptor (EGFR) mutations." (PMID 33816581, 2021). "Our combined preclinical and clinical results provide robust characterizations of EGFR-D770>GY and other EGFR exon 20 insertion mutants with a resulting G770 equivalent change, which comprise approximately 4% of all EGFR exon 20 mutations in lung cancer." (PMID 34944068, 2021). "The median duration of time elapsed from diagnosis of EGFR-mutant lung cancer to the detection of acquired BRAF mutation was 33.8 months (95% CI: 9.0–99.1 months)." (PMID 34921211, 2021).
lung cancer (continued). "Treatment of advanced lung cancer has dramatically changed since the discovery of the EGFR gene mutation in the 2000s and various driver gene mutations, including ALK rearrangement." (PMID 33963234, 2021). "Several studies showed that in patients with EGFR-mutated lung cancer, osimertinib resistance can be promoted by MET amplification in around 20% of cases." (PMID 34298655, 2021). "Lung adenocarcinoma, the most common subtype of lung cancer, frequently harbors oncogenic driver mutations in the epidermal growth factor receptor (EGFR)." (PMID 34568058, 2021). "This treatment strategy is feasible like the one using EGFR tyrosine kinase for lung cancer with mutations in EGFR." (PMID 34445645, 2021). "For instance, an EGFR mutational rate of 16.6% was reported in a cohort consisting of 2105 lung cancer patients from 126 hospitals in Spain, where an extensive study analyzed the frequency of EGFR mutations during the period of 2005–2008." (PMID 33956842, 2021). "Lung cancer is often driven by molecular alterations, such as EGFR and KRAS mutations, and ALK rearrangements expressed in tumor tissues of patients with NSCLC." (PMID 34722241, 2021). "Recently, it was described in EGFR-mutated lung cancer cells that the up-regulation of CBL proto-oncogene c (CBLC) contributes to tumor progression due to dysregulation of activated EGFR." (PMID 34487971, 2021). "The EGFR mutation rates have been variable according to ethinicty with higher frequency in Asian as compared with western lung cancer patients." (PMID 33639678, 2021). "When comparing urine to blood samples, other studies demonstrated the good agreement for the detection of EGFR mutation in lung cancer patients in these two body fluids." (PMID 34206947, 2021). "In this study, we focused on the association of ANXA1 and chemosensitivity to Osimertinib in NSCLC lung cancer cells with EGFR mutations." (PMID 34439260, 2021). "For example, clinical trials of tepotinib for MET-positive EGFR mutation-positive lung cancer after resistance to EGFR-TKIs are underway." (PMID 34440540, 2021). "Even in the early stages of lung cancer among patients with EGFR mutations, a high number of truncal mutations and overall mutation burden were significantly related to shorter overall survival." (PMID 33982444, 2021). "In this study, we report our experience with a lung cancer patient with an EGFR-L747P mutation diagnosed as EGFR-del19 by routine PCR-based diagnostic tests." (PMID 33863983, 2021). "For example, EGFR–TKI resistance mutation EGFR T790M has been detected in the CSF ctDNA of lung cancer patients." (PMID 33919036, 2021). "Subsequent studies analyzing molecular alterations in the tumors of lung cancer patients who had an excellent response to EGFR TKIs revealed the presence of unique mutations in EGFR that conferred high sensitivity to EGFR TKIs." (PMID 34202748, 2021). "Another limitation is represented by the clinical and biological heterogenicity of both breast and lung cancer; the choice of a precise histotype (adenocarcinoma) and a molecular subgroup (EGFR mutated) also aims to simplify this heterogeneous landscape." (PMID 34590588, 2021). "None of them demonstrated the independent prognostic role of EGFR mutation in the setting of TKI treatment for lung cancer patients admitted to the ICU due to respiratory failure." (PMID 34680533, 2021). "The molecular testing of lung cancer usually screens for genes encoding epidermal growth factor receptor (EGFR), anaplastic lymphoma kinase (ALK) and Kirsten rat sarcoma viral oncogene homolog (KRAS)." (PMID 33747933, 2021). "With the increasing availability of TKIs with intracranial penetration, the prognosis of brain metastasis (BM) lung cancer patients harboring EGFR mutations has improved." (PMID 35201504, 2021). "Here we tested the efficacy of inhibiting cyclin-dependent kinase 9 (CDK9) on lung cancer cell lines with K-Ras and EGFR mutations and on lung cancer organoids." (PMID 34359807, 2021).
lung cancer (continued). "EGFR is the most commonly mutated gene in early lung cancer, and thus we further analyzed its subtypes." (PMID 34109114, 2021). "In the commonly used lung cancer cell lines, H1975 carries both EGFR-L858R drug-sensitive mutation and EGFR-T790M drug-resistant mutation." (PMID 34391435, 2021). "Further studies are needed to investigate the clinicopathological factors of lung cancer patients who are clinically relevant for sputum-based EGFR mutation testing." (PMID 33757469, 2021). "In this study, we identified 22 EGFR germline mutations in 64 out of 31,906 Chinese patients with lung cancer." (PMID 34869019, 2021). "EGFR mutations have been found in lung cancer and they have been shown to have significant responses to EGFR tyrosine kinase inhibitors (TKIs), such as gebitinib and erlotinib." (PMID 33429909, 2021). "Afatinib showed favorable ORR and PFS regardless of the tumor EGFR mutation status results, similar to the findings of previous trials assessing afatinib as first‐line treatment of EGFR‐mutated non‐small cell lung cancer based on tumor genotyping." (PMID 33270375, 2021). "Almost 50% of Asian lung cancer patients harbor tumors with TKI-sensitizing EGFR mutation positive NSCLC, whereas prevalence of the EGFR mutations in Western lung cancer patients was about 15%." (PMID 33428651, 2021). "Osimertinib was originally approved as a second-line EGFR-TKI for patients with lung cancer with EGFR mutations that acquired resistance to first or second-generation EGFR-TKIs through the T790M secondary mutation." (PMID 33572269, 2021). "Kinase inhibitors of EGFR are used in EGFR mutated lung cancer patients, and EGFR targeting monoclonal antibodies are used in colorectal cancer patients in combination with chemotherapy." (PMID 33777943, 2021). "The standard of care for lung cancers with EGFR mutations is EGFR tyrosine kinase inhibitor (TKI) monotherapies." (PMID 33572269, 2021). "As another example, HCC827 is a lung cancer cell line driven by activating EGFR mutations (e.g., del E746-A750 and L859R), and thus demonstrated potent inhibition (nM range IC50) by gefitinib." (PMID 34502481, 2021). "In lung cancer, the detection of hotspot mutations in driver genes such as EGFR was used as guidance for targeted therapy." (PMID 33628109, 2021). "Lung cancers with activating mutations of EGFR are treated with TKIs, which target the activity of the receptor." (PMID 34359849, 2021). "But in lung cancer, the tyrosine kinase domain of the EGFR gene mutations was correlation with clinical efficacy of EGFR inhibitors." (PMID 33639651, 2021). "We discovered that EGFR mutation led to lung cancer with alveolar or bronchiolar features, which can originate from AT2 cells or BASCs, but not basal cells or club cells of the trachea." (PMID 34622577, 2021). "EGFR exon 19 deletion and L858R are the first and second most common mutations found in Asian lung cancer patients, respectively." (PMID 34199654, 2021). "The C797S mutation is located in the EGFR tyrosine kinase region, which can inhibit the effect of osimertinib and mediate the drug resistance of lung cancer cells." (PMID 33992097, 2021). "Lung cancer patients with sensitizing driver mutations in the epidermal growth factor receptor (EGFR) gene make up approximately 15% of the NSCLC patient overall." (PMID 33804721, 2021).